CD4 (CD4 molecule)
Diseases named in the same sentence as CD4 in open-access papers (continued):
Sharing a sentence is not in itself a finding about the gene and the disease.
B-cell lymphoma (continued). "CD4+ T-cell subsets are found in the tumour microenvironment (TME) of low-grade B-cell non-Hodgkin’s lymphomas such as marginal zone lymphoma (MZL) or follicular lymphoma (FL)." (PMID 29293620, 2018). "In the present study, we found that interleukin (IL)-10, which is increased in the serum of patients with B-cell NHL, induced the development of the CD4+HLA-DRlow/− population." (PMID 26230952, 2015). "Although Rituximab is used for treatment of B-cell lymphomas in HIV-infected patients, it is controversial and associated with high risk of infections in patients with blood CD4+ T-cell counts <100 cells/mm3." (PMID 26107380, 2015). "This phenomenon involves both classical and non-classical HLA class-II proteins and leads to the increase in the HLA class-II antigen processing in B-cell lymphomas and their subsequent recognition by CD4+ T cells." (PMID 24658441, 2014). "Using a mouse B-cell lymphoma model, we provided clear evidence that PD1high CD4+ T cells constituted a fraction of tumor antigen-experienced cells and were associated with downregulation of IL7 receptor and elevated level of apoptosis." (PMID 22400040, 2012). "On the contrary, in the 38C13 as well as in the A20 murine B cell lymphoma models, protection was found to be dependent on CD4+ and CD8+ T cells, when animals were vaccinated with a DNA construct encoding the scFv-Id fused to two different chemokines." (PMID 23162790, 2012). "Suppression mediated by CD4+CD25+ Treg co-cultured with allogeneic CFSE-labeled CD4+CD25− responder cells was also higher in involved lymphatic tissues from B-cell NHL than that mediated by Treg from HVs." (PMID 22174855, 2011). "We found a significantly higher percentage of CD4+CD25+FoxP3+CD127lo Treg presented in PB as well as BM samples from B-cell NHL compared with PB samples from HVs." (PMID 22174855, 2011). "In B-cell NHL, several studies have also shown that increased frequencies of CD4+CD25+ Treg in peripheral blood (PB) and involved LNs mediated vigorous suppressive activity compared to those from healthy volunteers (HVs)." (PMID 22174855, 2011). "We have shown that the expression of PD-1 on CD4+CD25+ Treg was higher in patients with B-cell NHL than in HVs, which strongly suggested a role for PD-1 and B7-H1 interaction in Treg cell-mediated suppression in B-cell NHL." (PMID 22174855, 2011). "Besides direct inhibition of B‐cell lymphoma, downregulation of regulatory T‐cells and repolarization of CD4‐positive T‐cells from Th‐2 to Th‐1 has been observed during ibrutinib treatment for FL and CLL." (PMID 41439214, 2025). "Hence, an abundance of GZMA+GZMK+ cytotoxic CD4+ and CD8+ T cells was associated with poor survival of B-cell NHL patients." (PMID 41030456, 2025). "By elucidating this immune evasion pathway, our work may uncover new targets for immunotherapy and improve strategies to harness CD4+ T cells against malignant B-cell lymphomas." (PMID 40801653, 2025). "Restoring effective CD4+ T-cell responses could enhance immunotherapy efficacy, offering a promising approach to overcoming immune resistance in B-cell lymphomas." (PMID 40801653, 2025). "In this study we tested a hypothesis that B-cell lymphomas secrete previously unrecognized molecules that disrupt HLA class II antigen presentation, rendering tumor cells invisible to CD4+ T cells and fostering an immunosuppressive niche." (PMID 40801653, 2025). "In vivo study showed that combination therapy with QHF and ADM potently inhibited the growth of B cell lymphoma in a syngeneic murine model, and significantly increased the proportion of tumor infiltrating CD4+ and CD8+ T cells in the tumor microenvironment (TME)." (PMID 35818037, 2022).
B-cell lymphoma (continued). "No clear difference was observed between total lymphocyte and CD4+ lymphocyte counts for patients who did or did not develop secondary B cell lymphoma, and risk factors for development of secondary B cell lymphoma were not identified in this study." (PMID 29974231, 2019). "Since B-cell lymphomas may display an increased CD4+/CD8+ T-cells ratio with respect to rLNs, it is possible that in FLs miR-342 represents a signature associated with CD4+ T-cells." (PMID 29731996, 2018). "This study suggested that PD-1 and CTLA-4 might be associated with the suppression of antitumor immunity in dogs with B cell lymphoma, and particularly through CD4+ T cells." (PMID 30040869, 2018). "In the murine A31 B cell lymphoma and 5T33 myeloma models, protection induced by DNA vaccination with a scFv fused to potato X virus protein was clearly compromised upon in vivo depletion of CD4+ T cells." (PMID 23162790, 2012). "Here we measured the frequencies and suppressive function of Treg in PB, BM and involved lymphatic tissues of patients with B-cell NHL and determined whether malignant B cells could induce the conversion of Treg from CD4+CD25− T cells." (PMID 22174855, 2011). "Blocking the interaction of PD-1 and B7-H1 could reduce the conversion of Treg induced by malignant B cells in some cases of patients with B-cell NHL, which indicated that the Treg conversion of CD4+CD25− T cells might be mediated through the PD-1/B7-H1 pathway." (PMID 22174855, 2011). "The consequence of these overrepresented CD4+CD25+FoxP3+CD127lo Treg in B-cell NHL remains unknown." (PMID 22174855, 2011). "Evidence suggested that roflumilast increased the volume of B-cell lymphomas while decreasing CD3+ cell and CD4/CD8 ratios, indicating its potential immunosuppressive properties." (PMID 41602587, 2026). "This complements previous studies on the role of LMP1 in activating CD4+ and CD8+ CTLs, which primarily focused on their responses to LMP1/2A expressing B cell lymphomas." (PMID 40534857, 2025). "We prospectively evaluated CD4, CD8 T-cell and serological responses to the COVID-19 mRNA vaccine in a cohort of patients treated for a B-cell lymphoma with anti-CD20 therapy." (PMID 39902042, 2024). "Our in vitro data suggested that expression of mutant IRF8 in B cell lymphomas deregulates antigen processing/loading and ultimately presentation in an MHCII context thus eliciting a subpar CD4 response." (PMID 38996030, 2024). "An animal model of B-cell lymphoma suggests that the key to the establishment of anti-TME is CD4+ T cells and that CD4+ T cells are able to predict patient prognosis." (PMID 39464313, 2024). "The defective activation of CD4 (but not CD8) T cells by IRF8-mutant B cell lymphomas, together with the well-recognized role of MHCII deficiency in DLBCL biology, suggested that IRF8 variants may deregulate genes and processes that are involved in antigen loading/processing and/or presentation." (PMID 38996030, 2024). "In most cases, B cells serve as anticancer cells by inducing antigen-specific CD4+ and CD8+ T-cell responses as antigen-presenting cells, with the exception of B-cell lymphoma." (PMID 34393804, 2021). "Expression levels of TIM-3 in the B-cell lymphoma endothelium has been correlated with poor prognosis and TIM-3+ ECs suppressed the activation of CD4+ T cells inhibiting TH1 polarization in vitro and in vivo." (PMID 33842331, 2021). "Although BMTs are routinely applied to abrogate residual B-cell lymphoma cells, we used the CD8+CD4− JM6 thymoma cell line." (PMID 34721430, 2021). "Despite lower anti-gE antibody GMCs in non-Hodgkin B-cell lymphoma (NHBCL) patients, CD4[2+] T-cell frequencies were similar between NHBCL and other underlying diseases." (PMID 34406911, 2021). "We found a significant decrease in all subpopulations of EBV-specific CD4+ T cells from HIV+ patients at stage 3 and with B-cell lymphoma." (PMID 30337929, 2018).
B-cell lymphoma (continued). "A previous report has shown that the immunoinhibitory receptor programmed death-1 (PD-1) is upregulated in CD4+ and CD8+ T cells and is involved in the exhaustion of T-cell functions in BLV-infected cattle bearing B-cell lymphoma." (PMID 29914540, 2018). "This group also implicated the CD8+CD122+ population, suggesting it plays a key role in restricting expansion of CD4+ICOS+ T cells, antibody production, and development of B cell lymphomas." (PMID 28098193, 2017). "In the present study, we comprehensively evaluated the expression of T-cell markers (CD2, CD3, CD4, CD5, CD7, and CD8) in 501 B-cell lymphomas, including 225 DLBCLs, by flow cytometry and subsequent immunohistochemistry." (PMID 28380441, 2017). "To examine the role of GzmB in GVT effect mediated by CD4+CD25− Tcon cells, we utilized A20 tumor cells, which are B cell lymphoma cells derived from BALB/c strain and express normal level of MHC class II." (PMID 27774524, 2016). "In this preclinical model, CD4+ and CD8+ T cells mediate immune control over EBV infection and B-cell lymphoma development and protective EBV-specific CD4+ T cells can be primed with vaccine candidates." (PMID 24999343, 2014). "In addition, NFATC3 was hypothesized as being part of a mechanism whereby intratumoural CD4+CD25+ T-cells (Treg cells) interact with activated CD4+ T-cells to suppress the anti-tumour activity of infiltrated CD4+ T-cells in B-cell NHL tumours and thus, induce immune tolerance to these tumours." (PMID 24885312, 2014). "Using biopsy specimens from patients with B-cell NHL, we observed that TGF-β profoundly inhibits the proliferation of both CD4+ and CD8+ T cells stimulated by anti-CD3 and CD28 Abs." (PMID 23555036, 2013). "In B cell lymphoma lines, manipulations that increase MHC class II and GILT expression improve CD4+ T cell recognition." (PMID 24409177, 2013). "As the suppressive function of Treg is associated with its surface receptors, we evaluated a possible role of surface markers in CD4+CD25+CD127lo Treg and CD4+ T cells presented in patients with B-cell NHL." (PMID 22174855, 2011). "Conversely, CD4+ or CD4+CD8+/− T-LGL leukemia has an indolent course and is frequently characterized by lymphocytosis with normal hemoglobin and platelet count and by the presence of a second neoplasms, especially B-cell NHL." (PMID 34572739, 2021). "Furthermore, MIMIC found a group of cells consists of A20 (B-lymphoma cell), CH12.LX (CH12 B cell lymphoma), B cell (CD43-), B cell (CD19+), Spleen, T-Naive (CD4+), Thymus." (PMID 34180954, 2021). "Median trough CD4+ lymphocyte counts in patients who did (n = 5) or did not (n = 42) develop secondary B cell lymphoma were 44 per mm3 (range, 18–162) and 51/mm3 (range, 5–3274), respectively." (PMID 29974231, 2019). "The α4β7-expressing RPMI8866 cell line was derived from a human B cell lymphoma, and expresses α4β7, but no detectable CD4 or CCR5." (PMID 30153309, 2018). "This is supported by the observation that PD1 and Foxp3 have a nonoverlapping expression pattern in CD4+ T cells infiltrating B-cell lymphoma." (PMID 22400040, 2012). "For this purpose we selected the RPMI-8866 B cell lymphoma cell line that is known to express α4β7, but does not express CD4, the receptor for HIV-1." (PMID 22720026, 2012). "To investigate a possible role of CD4+CD25+FoxP3+CD127lo Treg in the immune system in B-cell NHL, both peripheral tolerance and the tumor microenvironment, we measured the frequencies of CD4+CD25+FoxP3+CD127lo Treg in PB, BM and involved lymphatic tissues from patients with B-cell NHL." (PMID 22174855, 2011). "Taken together, our results suggest that malignant B cells induce the conversion of CD4+CD25− T cells to Treg, which may play a role in the pathogenesis of B-cell NHL and represent a promising therapeutic target." (PMID 22174855, 2011).
B-cell lymphoma (continued). "Expression of IRF8 mutants in murine B cell lymphomas suppressed CD4, but not CD8, activation elicited by antigen presentation and downmodulated CD74 and human leukocyte antigen (HLA) DM, intracellular regulators of antigen peptide processing/loading in the major histocompatibility complex (MHC) II." (PMID 38996030, 2024). "Moreover, it was also shown that these cells are memory T cells characterized by a CD4+/CD45RO1 phenotype, and further studies showed that an increased number of activated memory CD4+ T cells infiltrating areas of B-cell lymphoma correlates with a lower proliferative rate of cells." (PMID 32731512, 2020). "However, by using a chimeric mouse/human IgG DNA vaccine delivered by intramuscular injection, it was shown that protection in the 38C13 murine B cell lymphoma model was not impaired by CD4+/CD8+ T cell depletion." (PMID 23162790, 2012). "In summary, we have showed an increased frequency and suppressive activity of CD4+CD25+FoxP3+CD127lo Treg in PB, BM, and involved lymphatic tissues from patients with B-cell NHL, which might play a critical role in suppressing the host immune responses to tumor." (PMID 22174855, 2011). "Here we demonstrated that CD4+CD25+FoxP3+CD127lo Treg were markedly increased and their phenotypes were different in peripheral blood (PB) as well as bone marrow (BM) from newly diagnosed patients with B-cell NHL compared with those from healthy volunteers (HVs)." (PMID 22174855, 2011). "In agreement with the mouse B cell lymphoma models, IRF8-mutant DLBCLs displayed significantly diminished signatures of NK cell infiltrate as well as selected CD4 subpopulations, including TH1, but not TH2." (PMID 38996030, 2024). "Positive expression of CD11a, CD79α, CD45, CD45RA, and MHCII and no expression of CD3, CD4, CD5, CD8, CD11d, CD14, CD21, CD34, and CD56 classifies it as a B-cell lymphoma." (PMID 27639374, 2016). "Therefore, the expression of T-cell markers other than CD5, such as CD2, CD4, CD7, and CD8, has not been broadly investigated in a large case series of B-cell lymphomas." (PMID 28380441, 2017). "Last, to mitigate concerns that the ectopic expression of CD74 may enhance CD4 activation irrespective of IRF8 status, and to define whether CD74 can rescue the IRF8-mutant phenotype, we tested CD74 effects on B cell lymphoma models expressing IRF8 WT, the DBD mutant N87Y, or the CTD mutant I424T." (PMID 38996030, 2024).
myocardial infarction (73 papers, 2011 to 2026). Gross necrosis of the myocardium, as a result of interruption of the blood supply to the area, as in coronary thrombosis. "As cardiac cDC2s were largely unaffected by loss of IRF4 in the EAM model and myocardial infarction, it is also possible that cDC2s or MCs acted locally in the heart to activate effector autoreactive CD4+ T cells." (PMID 30524444, 2018). "Our finding is contrary to that observed by D’Ascenzo and colleague where CD4+ T cell count of < 200 cells/μl was associated with increased risk of myocardial infarction and cardiovascular instability." (PMID 26315756, 2015). "Using unbiased transcriptomic profiling of cardiac T cell subsets after myocardial infarction, we identified reticulocalbin 3 (Rcn3) as one of the most selectively and robustly upregulated genes in neonatal CD4+Foxp3+ T (T-reg) cells." (PMID 41597278, 2026). "Myocardial infarction was induced in mice of different ages, and T cell subsets (CD4+ T cells, CD8+ T cells, and CD4+Foxp3+ T [T-reg] cells) were analyzed using flow cytometry and RNA sequencing." (PMID 41597278, 2026). "According to another survey, CD4+ T cells can exert cardioprotective effects in preclinical models of acute myocardial infarction by acquiring the T regulatory phenotype and suppressing local inflammation, which consistent with out results." (PMID 41472876, 2025). "CD4+ Th cells play a critical role in the immune-inflammatory responses and cardiac remodeling during myocardial infarction and reperfusion injury." (PMID 38879568, 2024). "CD4+ Foxp3+ CD25+ T-cells (Tregs) promote the healing process after myocardial infarction by engendering a pro-healing differentiation state in myocardial monocyte-derived macrophages." (PMID 38436707, 2024). "It is well known that CD4+ T cell activation is beneficial for the recovery of myocardial wounds after myocardial infarction." (PMID 39350967, 2024). "CD4+ Th cells primarily impact three major events following myocardial infarction: inflammation, anti-inflammation, and remodeling/repair, exerting either promoting or inhibiting effects." (PMID 38879568, 2024). "The reported incidence of LVH in non-selected populations (including older patients with lower CD4+ count and already diagnosed with cardiovascular disease, such as heart failure or myocardial infarction) is higher." (PMID 38256597, 2024). "In addition, cardiac infiltration of CD4+ T cells is implicated in the healing process post-myocardial infarction (MI), contributing to cardiac fibrosis and dysfunction." (PMID 37681877, 2023). "CD4(+) T cells participate in cardiac healing after myocardial infarction but can also aggravate heart failure induced by pressure overload." (PMID 36232442, 2022). "In animals, who were studied during an experimental myocardial infarction, the participation of CD4+ T lymphocytes in repair processes and positive left ventricular remodelling after myocardial infarction was confirmed." (PMID 33150520, 2021). "In humans, circulating CD4+ effector memory T cell numbers correlate to the intima-media thickness and the occurrence of myocardial infarction and the number of CD4+ T cells in the plaque increases during lesion progression." (PMID 32872393, 2020). "Our results point to a significant role of heart infiltrating conventional CD4+ T-cells after myocardial infarction." (PMID 32298302, 2020). "Consistent with previous studies, we found that CD4+ T cells remarkably infiltrated in the heart of myocardial infarction." (PMID 32327611, 2020). "After myocardial infarction, CD4+ T cells were reported to stimulate collagen matrix formation and thereby improve wound healing and survival by reducing the risk of myocardial rupture." (PMID 31565659, 2019). "The percentage of CD4+ T cells (gated as CD4+ CD8–) was significantly increased, while CD8+ T cells (gated CD4- CD8+) percentage decreased 1 h after myocardial infarction, in comparison to pre-AMI levels." (PMID 30898123, 2019).